MSLN (mesothelin)
Diseases named in the same sentence as MSLN in open-access papers (continued):
Sharing a sentence is not in itself a finding about the gene and the disease.
tumor (continued). "Compared to control cells, MSLN-deficient HCC1806/HM3 cells showed significantly reduced IC50 values for Paclitaxel and Carboplatin, as well as decreased tumor cell viability, suggesting that combining MSLN deficiency with Paclitaxel and Carboplatin could be effective in TNBC liver metastases." (PMID 41513618, 2026). "Furthermore, the aberrant expression of MSLN in tumors is closely associated with malignant phenotypes, including tumor cell proliferation, invasion, and resistance to chemotherapy, thereby positioning it as a potential tumor-specific therapeutic target." (PMID 41400642, 2025). "In addition, the fact that MSLN-deficient cells led to a moderate but significant reduction in cell viability further supports the finding that MSLN loss suppresses tumor cell proliferation by inducing a senescent-like state rather than causing overt cytotoxicity." (PMID 40563707, 2025). "As MSLN is expressed on healthy pleural tissues, an inverse relationship between MSLN immunoreactivity and cellular atypia has been proposed, and it is possible that MSLN expression could be reduced as tumour cells become less differentiated, leading to an association with poorer prognosis." (PMID 37040900, 2023). "We report that the proportion of mesothelin-positive cells was 7.71%, 2.40% and 2.20% of myocardial cells, pulmonary cells and stomach cells, respectively, indicating that these organs could be at high risk of “on-target off-tumor” toxicity on anti-mesothelin CAR T cell therapy." (PMID 36059490, 2022). "Mesothelin is an especially appealing target antigen since several preclinical and clinical studies found that it was involved in the malignant transformation of tumors and had a clear association with tumor aggressiveness, which led to local invasion and eventual metastasis." (PMID 32914147, 2020). "Mesothelin-specific immune responses may also aid to identify patients i) at increased risk for tumor progression ii) who may benefit from a more frequent followup and alternate treatment strategies, including immunotherapeutic strategies with the aim to expand anti-cancer T-cells." (PMID 29854291, 2018). "Our previous results suggested that mesothelin might be a good target for control by an immune response, as mesothelin overexpression reliably caused a decrease in a heterotopic tumor growth in an immunocompetent syngeneic mouse model while in vitro proliferation was not inhibited." (PMID 29474384, 2018). "Mesothelin is an especially appealing target since several preclinical and clinical studies have found that it is involved in the malignant transformation of tumors and has a clear association with tumor aggressiveness, which leads to local invasion and eventual metastasis." (PMID 28862644, 2017). "Studies involving tumor-targeted probes against folate receptor alpha, α3-integrin, mesothelin, and CA125 were included, with emphasis on probe design, delivery, imaging performance, safety, and clinical relevance." (PMID 42198268, 2026). "The top 30 upregulated genes were visualized in a heatmap; MSLN was significantly altered in the metastatic cells compared to their primary tumor cells (hereinafter referred to as Pri or Pri cells)." (PMID 41513618, 2026). "Using RNA sequencing of metastatic 4T1-HM3 and primary 4T1-Pri tumor cells, mesothelin (MSLN) was identified as significantly upregulated in metastatic TNBC cells and tissues, as confirmed by qRT-PCR, Western blot, and immunohistochemistry." (PMID 41513618, 2026). "Single-targeting MSLN is prone to antigen escape and drug resistance due to tumor heterogeneity, while tumor microenvironment immunosuppression can further impair the efficacy of immunotherapies such as CAR-T." (PMID 41400642, 2025). "This study provides the first evidence that MSLN can be transferred from tumor cells to immune cells through EVs." (PMID 41226368, 2025).
tumor (continued). "Early data have demonstrated that mesothelin-directed CAR T-cells can mediate tumor lysis, although CRS was noted in a small number of patients." (PMID 40940995, 2025). "MSLN also promotes tumor invasion by upregulating matrix metalloproteinases, which facilitate this process by degrading the extracellular matrix." (PMID 41400642, 2025). "designed a novel third-generation TanCAR targeting both FOLR1 and MSLN, combined with IL-12 secretion, to reduce the likelihood of tumor antigen escape and enhance CAR-T cell infiltration and antitumor activity." (PMID 40092990, 2025). "MSLN drives tumor progression by regulating malignant phenotypes such as tumor cell proliferation, invasion, and metastasis, and its expression level is also a potential prognostic biomarker for patients." (PMID 41400642, 2025). "For instance, MSLN and miR-198 have an inverse relationship where miR-198 functions as a tumor suppressor by regulating genes involved in cell proliferation, migration and survival." (PMID 40227616, 2025). "Using copyKAT copy number variant analysis, we identified T2, T3, T4, and T6 as the malignant tumor clusters with high expression of MSLN." (PMID 40315330, 2025). "In additional orthotopic mouse models, they confirmed that the use of MSLN Ab reduces tumor weights and reduced Tregs while increasing CD8+ T cells." (PMID 40523922, 2025). "Our findings demonstrate that anti-MSLN uCAR-like NK cells not only possess exceptional tumor penetration and homing capabilities but also exhibit potent antitumor activity against MSLN-positive tumors, laying the foundation for their clinical application." (PMID 41436559, 2025). "Building on these findings, this study developed a strategy utilizing MSLN/CD3 bsAb to activate and recruit specific subsets of NKT or Vγ9Vδ2 T cells, thereby effectively identifying and eliminating MSLN-positive tumor cells." (PMID 39995672, 2025). "The cytotoxicity of BBζ and BBζ-Neo were measured by co-culturing them with MSLN-positive tumor cells (AsPC-1, MSLNOE PANC-1 or MSLNOE BxPC-3) for 4 hours at an effector to target ratio (E:T) of 1:1 or 5:1." (PMID 40025022, 2025). "The binding of MSLN to MUC16 not only enhances the adhesion ability of tumor cells but also upregulates the expression of MMP7 through the PI3K/AKT signaling pathway, thereby strengthening the invasive capacity of these tumor cells." (PMID 41400642, 2025). "Among these, MSLN acts as a crucial immunomodulatory molecule that shapes the immunosuppressive tumor microenvironment through various pathways." (PMID 41400642, 2025). "qPCR analysis confirmed that the expression level of MSLN in apCAFs was more than five times higher comparing to the unsorted tumor cells." (PMID 39887656, 2025). "Another engineered Listeria monocytogenes, JNJ-64041757, which expresses human mesothelin, can induce cellular immunity against mesothelin-expressing tumor." (PMID 41516132, 2025). "Targeted therapy represents a crucial direction for future cancer treatment, and the differential expression pattern of MSLN in tumor tissues offers a highly attractive opportunity for the targeted therapy of various malignant tumors." (PMID 41400642, 2025). "Not only did they observe an increase of CAR T infiltration into tumors but also saw an increase in tumor mesothelin expression following RT, further augmenting CAR-mediated antitumor responses." (PMID 40636106, 2025). "It systematically evaluates the results of studies targeting key tumor-associated antigens, such as EGFR, IL13Rα2, GD2, B7-H3, CEA, MSLN, PSCA/PSMA, and ROR1." (PMID 40969260, 2025). "Together, our data demonstrate that anti-MSLN CAR-like NK cells exhibit specific and potent antitumor activity against MSLN-positive tumor cells in vivo." (PMID 41436559, 2025). "The results showed that after αMSLN treatment, both the number of apCAFs and the expression of MSLN were decreased within the tumor." (PMID 39887656, 2025).
tumor (continued). "In hematological malignancies, the most commonly targeted proteins include CD19, BCMA, and CD22, whereas in solid tumors, tumor-associated antigens (TAA), HER2, and mesothelin (MSLN) are frequently targeted." (PMID 40469307, 2025). "The Tmod system pairs an inhibitory CAR recognising HLA‐A*02 (commonly lost in tumours) with an activating CAR targeting an antigen such as mesothelin or carcinoembryonic antigen." (PMID 41292193, 2025). "It was found that MSLN manifest was related to the female gender and inversely correlated with solid/sheet-like tumor proliferation." (PMID 40227616, 2025). "Previous studies have shown that MSLN affects pancreatic cell proliferation and migration and plays a role in tumor progression and chemoresistance." (PMID 40266223, 2025). "In patient-derived xenograft tumor models, AR demonstrated high affinity for MSLN and was able to specifically recognize and kill MSLN-expressing tumor cells." (PMID 41400642, 2025). "MSLN protein expression was validated on primary EOC cells isolated from tumor tissue and ascites by MPFC (median MFI ratios 2.2 and 4.0, respectively)." (PMID 40402266, 2025). "The specificity of the anti-mesothelin antibodies allowed the APMS to efficiently reach the tumor cells, delivering doxorubicin directly to them while minimizing collateral damage to healthy cells." (PMID 40918456, 2025). "Over time, the CAR target—particularly MSLN—can be significantly downregulated or shed from the tumor cell surfaces (temporal heterogeneity), and its expression can also vary between different tumor cells within the same patient (spatial heterogeneity)." (PMID 40366419, 2025). "The results revealed that anti-MSLN CAR-like NK cells significantly inhibited the growth of MSLN-high-expressing tumor cells, whereas tumors in the control group progressed rapidly." (PMID 41436559, 2025). "Mesothelin-targeted TRuC has demonstrated a reduction in tumor volume, enhanced tumor infiltration, and improved T cell persistence in vitro as well as in preclinical models." (PMID 41375064, 2025). "In vivo studies have shown that anetumab ravtansine specifically localizes to MSLN-positive tumors and effectively inhibits tumor growth in subcutaneous and orthotopic xenograft models." (PMID 40362535, 2025). "Epithelial-mesenchymal transition (EMT) is an early event in tumor metastasis, regulated by various molecules, including MSLN." (PMID 41400642, 2025). "Mesothelin has emerged as a compelling marker and target across multiple malignancies due to its high tumor specificity and elevated expression in advanced cancers." (PMID 40427042, 2025). "Using flow cytometry, specific binding of A101 to mouse and human mesothelin was confirmed on several mouse and human-derived tumor cell lines." (PMID 40568084, 2025). "We next visualized iNK tumor infiltration in situ using multiplex immunofluorescence staining for MSLN (tumor marker), hCD45/hCD56 (NK marker), and Ki67 (proliferation marker)." (PMID 40315330, 2025). "Anetumab ravtansine, a human anti-mesothelin antibody conjugated to a tubulin inhibitor named ravtansine, binds to mesothelin with high affinity and exerts a bystander effect on neighboring tumor cells." (PMID 41375064, 2025). "With high expression of RIAD and CXCR3, MesoCAR-RIAD T cells show an enhanced trafficking and infiltration ability compared with mesoCAR T cells and exhibit enhanced tumor killing ability against mesothelin positive tumor cells." (PMID 40148310, 2025). "Anetumab ravtansine was evaluated in a phase II multicenter study involving mesothelin positive (defined as 2+ or 3+ mesothelin membrane staining in at least 30% of viable tumor cells) patients with PM previously treated with platinum-based therapy." (PMID 41375064, 2025).
tumor (continued). "These BiTE can recruit and activate bystander T cells in the tumor microenvironment to attack tumor cells that lack MSLN expression but express NKG2D ligands, thereby demonstrating superior tumor clearance and survival benefits in heterogeneous tumors." (PMID 41400642, 2025). "CAR-T therapies target tumor-associated antigens including KRAS G12D, mesothelin, EGFR, HER2, and CLDN18.2, with early trials reporting partial responses and stable disease." (PMID 40806185, 2025). "CAR-T cells targeting mesothelin have shown potential in reducing tumor burden, though their success has been hindered by the highly immunosuppressive TME and off-target toxicity." (PMID 40013133, 2025). "Crucially, in vitro validation confirms that CTHRC1+ CAFs secrete WNT5A, which upregulates the mesothelin (MSLN) gene in CRC tumor cells - an effect abolished by WNT5A inhibition or CTHRC1 knockdown." (PMID 41450739, 2025). "While our understanding of the physiological functions of MSLN remains limited, there is considerable interest in defining its role in tumor pathology." (PMID 41335396, 2025). "Another therapy intended for use either in combination with a standard anti-tumor modality or as a stand-alone treatment is Isocel, which is an anti-mesothelin CAR γδ T cell therapy that began phase 3 clinical trials during the fourth quarter of 2023." (PMID 40148988, 2025). "In vitro, anti-MSLN CAR-like NK cells demonstrated selective cytotoxicity against MSLN-positive tumor cells through stable binding with MSLN×CD16A while sparing MSLN-negative cells." (PMID 41436559, 2025). "The membrane-distal region (MDR), which binds to MUC16, is represented by region I. The MSLN MDR has emerged as the primary target for current immunotherapy approaches because of the role the MSLN–MUC16 relationship plays in tumor development." (PMID 40227645, 2025). "Anti-MSLN uCAR-like NK cells, endowed with tumor-penetrating capabilities, are able to infiltrate tumor tissues and induce tumor regression, providing a solid foundation for the clinical application of immunotherapies targeting MSLN-positive solid tumors." (PMID 41436559, 2025). "To construct the bispecific cell engager MSLN×CD16A, we utilized the SpyTag/SpyCatcher protein conjugation system to combine MSLN-SpyCatcher (for tumor localization and aggregation) and CD16A-SpyTag (for immune activation) at a molecular ratio of 1:1." (PMID 41436559, 2025). "By activating the STAT3-cyclinE/CDK2 signaling axis, MSLN accelerates cell cycle progression, thereby promoting tumor cell proliferation." (PMID 41400642, 2025). "The proportion of T3, which expressed the highest level of MSLN among all the tumor subclusters, was significantly reduced after MSLN.CAR-IL-15 GR1.1-iNK treatment." (PMID 40315330, 2025). "Approximately 80% of PDAC patients’ tumor tissues express MSLN, rendering it a promising target with broad application potential (NCT03198546)." (PMID 40969260, 2025). "We evaluated the tumor killing and cytokine release mediated by the MSLN/CD3 bsAb in a co-culture assay using four MSLN+ tumor cell lines (KLM-1, T3M4 and H9) incubated with different subsets of T cells in the presence of the MSLN/CD3 bsAb." (PMID 39995672, 2025). "Malignant epithelial cells expressed secretory markers including EPCAM, cytokeratins (KRT8/10/18), MUC16, the carrier of the CA125 tumor marker, and mesothelin (MSLN), an OC differentiation antigen." (PMID 40164596, 2025). "A phase I study evaluated gavo-cel in previously treated mesothelin-expressing (defined as 2+ or 3+ mesothelin expression by IHC staining in ≥50% of tumor cells) solid tumor patients, 23 of whom had PM." (PMID 41375064, 2025). "Compared with the PBS control, both types of NK cell therapy (NK + MSLN×CD16A and anti-MSLN CAR-like NK) significantly delayed tumor growth." (PMID 41436559, 2025). "In mice treated with SS1P, a MSLN immunotoxin, sMSLN surrounding the tumor and in the blood blocked the cytotoxic effects of SS1P21,22." (PMID 40240561, 2025).
tumor (continued). "Mesothelin is an ideal target due to its restricted expression in tumor cells and its role in tumor progression." (PMID 40940995, 2025). "Nevertheless, off-tumor toxicity remains a challenge and a complex event to elucidate, requiring improved preclinical investigations to mitigate its impact with MSLN-positive tumors." (PMID 41335396, 2025). "An ongoing phase I/II trial is currently evaluating this TRuC chimeric switch receptor in individuals with 1+, 2+, or 3+ mesothelin expression in at least 50% of tumor cells by IHC (NCT05451849)." (PMID 41375064, 2025). "MSLN also upregulates CD24 expression via the activation of the Wnt/β-catenin pathway, which induces pro-tumor M2 polarization of tumor-associated macrophages." (PMID 41400642, 2025). "The constructed anti-MSLN CAR-like NK cells exhibited excellent tumor control both in vitro and in vivo." (PMID 41436559, 2025). "MUC1 and mesothelin are tumor markers with potential targeting for ADCs, which have shown good results in clinical studies." (PMID 40507272, 2025). "Collectively, these studies illuminate the diverse mechanisms through which MSLN facilitates tumor immune escape, providing a crucial foundation for developing MSLN-targeted immunotherapy strategies." (PMID 41400642, 2025). "Analysis of TNBC tissues using The Cancer Genome Atlas and tumor microarrays revealed high but weakly correlated expression of MSLN and NKG2DL, making them ideal targets for dual engagement." (PMID 40033418, 2025). "Elevated MSLN expression correlates strongly with reduced CD8+ T cell infiltration in the tumor microenvironment and poor patient prognosis." (PMID 41400642, 2025). "The rationale is to redirect T-cells to tumor cells overexpressing MSLN, leading to T-cell-mediated cytotoxicity and tumor cell elimination." (PMID 39995672, 2025). "Future research needs to conduct in-depth comparative analyzes of MSLN's signaling regulatory networks in different tumor microenvironments to clarify the specific conditions under which it exerts its oncogenic effects." (PMID 41400642, 2025). "One strategy involves engineering dual or tandem CAR-T cells, where two distinct CARs (e.g., mesothelin and FRα) are expressed on the same T cell, ensuring that tumor cells with heterogeneous antigen expression remain vulnerable to attack." (PMID 40643516, 2025). "CAR-NK cells also target solid tumor antigens such as HER2, EGFR and mesothelin, showing effective tumor infiltration and anti-tumor responses." (PMID 40155973, 2025). "In the subcutaneous MKN45 (MSLN+) xenograft model, anti-MSLN uCAR-like NK cells significantly inhibited tumor growth with good tolerability." (PMID 41436559, 2025). "Mesothelin (MSLN), a glycoprotein-based tumor antigen, is elevated in several malignancies and it is related to a poor prognosis, as it enhances tumor aggression, dissemination and chemotherapy resistance." (PMID 40227616, 2025). "Accumulating evidence indicates that MSLN orchestrates the phenotypes and functions of various immune cells within the tumor microenvironment, thereby fostering a complex immunosuppressive milieu." (PMID 41400642, 2025). "The MSLN/CD3 bsAb significantly inhibited the tumor growth of H9 cells in the presence of PBMC, and this effect was dose-dependent." (PMID 39995672, 2025). "We found that a brief exposure to EVs derived from EZH2 inhibitor-treated cells skewed naïve neutrophils toward a pro-tumor phenotype characterized by high levels of PD-L1 and MSLN (Mesothelin) expression on the surface." (PMID 41226368, 2025). "ADCs achieve tumor‐specific cytotoxicity by linking antibodies targeting MSLN with cytotoxic agents, combining targeting precision with potent cellular toxicity." (PMID 40904706, 2025). "While its oncogenic properties have been documented, the role of MSLN in regulating cellular senescence—a tumor-suppressive mechanism—has remained unexplored." (PMID 40563707, 2025).